EPCAM (epithelial cell adhesion molecule)
Diseases named in the same sentence as EPCAM in open-access papers (continued):
Sharing a sentence is not in itself a finding about the gene and the disease.
tumor (continued). "Besides being the “epithelial marker”, dual properties of tumor “biomarker” of both EpCAM and CKs have been demonstrated." (PMID 26718583, 2015). "Additionally, an anti-EpCAM antibody was used to identify epithelial tumor cells in each disaggregated tissue." (PMID 25807104, 2015). "However, it has been recognized that during progression of EMT, down-regulation of EpCAM and CK is part of an oncogenic pathway that increases tumor invasiveness and metastatic potential." (PMID 26267323, 2015). "EpCAM is expressed in many epithelial tumors and thus is a widely used tumor marker." (PMID 26498594, 2015). "It is reasonable to speculate that bio-characterization of CTCs isolated by anti-EpCAM might be perturbed with unpredictable artifacts upon antibody binding to EpCAM, an active signaling molecule on tumor cells." (PMID 26718583, 2015). "Moreover, only CD117+ cell levels decrease substantially after prostatectomy, which, together with EpCAM positivity, confirm their tumor origin." (PMID 25595903, 2015). "However, it was observed that the EpCAM+ epithelial cell population decreased from >75% of cells in the original tumour specimens to <15% in all five spheroid samples, yet total ALDH activity was increased." (PMID 25658706, 2015). "The release of EpEX may further enhance EpCAM cleavage and trigger EpICD-mediated signaling in an autocrine or paracrine manner, which would consequently promote tumor initiation and progression." (PMID 26317650, 2015). "Indeed, these HCC differ from those in adults, with a nearly constant expression of stem/progenitor cell markers such as EpCAM, which was expressed in 14 out of the 16 tumours in our paediatric study." (PMID 26110787, 2015). "Interestingly, γSMA expression in HCC tumour cells was strongly associated with stem/progenitor cell markers, namely CK19 and EpCAM." (PMID 26110787, 2015). "Solitomab, which targets epithelial-cell-adhesion-molecule (EpCAM) on tumor cells while also containing a CD3 binding region, is being pursued as treatment for metastatic, recurrent, or persistent USC overexpressing EpCAM (86 % of USC cell lines tested by flow cytometry)." (PMID 27231571, 2015). "No published study has demonstrated direct induction of cancer cell apoptosis by anti-EpCAM antibodies in a clinical setting, and so it remains unclear whether such antibodies can directly inhibit tumor cell proliferation." (PMID 26317650, 2015). "EpCAM expressing circulating tumor cells, detected by CellSearch, are predictive of short survival in several cancers and may serve as a liquid biopsy to guide therapy." (PMID 26184843, 2015). "Moreover, heterogeneity of chromosome and tumor biomarker of CTCs/DTCs cannot be co-examined by conventional CK/EpCAM-dependent techniques." (PMID 26718583, 2015). "The exclusion of circulating tumor cells (CTCs) that have lost epithelial antigens during the epithelial-to-mesenchymal transition (EMT) process by using Epithelial Cell Adhesion Molecule (EpCAM) based capture methods is still a matter of debate." (PMID 26571236, 2015). "EpCAM-positive circulating tumor cells (CTC) reflect disease status in several epithelial tumors." (PMID 26299616, 2015). "We evaluated the expression levels of EpCAM and the in vitro activity of solitomab, a bispecific single-chain antibody construct which targets epithelial-cell-adhesion-molecule (EpCAM) on tumor cells and also contains a CD3 binding region, against primary uterine and ovarian CS cell lines." (PMID 26474755, 2015). "The life expectancy is often very short and there is a need for verification of additional parameters, like EpCAM expressing tumor cells that may help to identify patients who benefit most from catumaxomab treatment." (PMID 25947366, 2015). "Several studies have investigated the role of EpCAM as a membrane-bound protease inhibitor, a function that may serve to protect tumor cells from their own secreted cathepsins during metastasis." (PMID 26317650, 2015).
tumor (continued). "Furthermore, we identified the specific tumor marker, EpCAM, on the tumor-cell surface through the microfluidic technology using miniaturized nanoliter reaction droplets." (PMID 26487959, 2015). "Here, EpCAM appears to be expressed in primary tumors and overt metastases, whereas intermediates of the metastatic cascade, i.e., circulating and disseminating tumor cells (CTCs/DTCs), might downregulate EpCAM to gain migratory and invasive properties." (PMID 25477371, 2015). "In conclusion, we described the development of an EpCAM-targeted immunotoxin with potent activity against tumor cells, which may lay the foundation for future development of therapeutic antibody for the treatment of EpCAM-positive tumors." (PMID 25960617, 2015). "Our results showed that the level of positive EpCAM staining increased with tumor stage." (PMID 26356670, 2015). "It has been considered that the detection methods for circulating tumor cells (CTCs) based on epithelial cell adhesion molecule (EpCAM) underestimate the number of CTCs and may miss a metastatic subpopulation with cancer stem cell (CSC) properties." (PMID 26317979, 2015). "Interestingly, this expression was significantly correlated with poor tumour differentiation and progenitor cell features characterized by the expression of EpCAM and K19." (PMID 26110787, 2015). "This technique might allow to further discriminate between tumor and benign cells, which both express the routinely used EPCAM cell surface protein." (PMID 25514598, 2015). "In order to isolate CTC from cancer patients affected by carcinoma, studies have advanced from Reverse Transcriptase-Polymerase Chain Reaction- (RT-PCR-) based methods to immunomagnetic enrichment of tumor cells exploiting the presence of molecular markers as EpCAM on the CTC surface." (PMID 26167450, 2015). "The immunotoxin can recognize EpCAM, and whether it is cytotoxic to EpCAM-positive tumor cells must be confirmed." (PMID 25960617, 2015). "Epithelial cell adhesion molecule (EpCAM) is known as a tumor stemness marker of HCC." (PMID 26165819, 2015). "Interestingly, the percentage of CD117+ cells that were EpCAM+ is exactly the same as the percentage of total CD117+ cells lost upon tumor removal, indicating that it is likely these cells of tumor origin that are absent in postoperative patients." (PMID 25595903, 2015). "During EMT, the expression of EpCAM in tumor cells will be down-regulated." (PMID 26317979, 2015). "Through this enrichment step, CD45+ cells were removed and CD45−/EpCAM+ tumor cells were enriched." (PMID 26702369, 2015). "As expected, the EpCAM+CD133+ cells demonstrated higher tumor-generating capacity (P<0.001)." (PMID 25938772, 2015). "The detection of the soluble EpCAM protein in body fluids might be used for the estimation of EpCAM high tumor cells in malignant ascites." (PMID 25947366, 2015). "Thus, soluble EpCAM is binding to the EpCAM-binding Fab domain of catumaxomab and is blocking this part of the antibody for interaction with the cell membrane of the tumor cell." (PMID 25947366, 2015). "Overall, the C-KIT+/EpCAM+/E-cadherin+/K7−/K19−/AFP−/albumin− immunotype suggested that the present tumor may have originated from transformed C-KIT+/EpCAM+ DE-like cells, which are more primitive and undifferentiated than bipotential HPCs." (PMID 25202388, 2014). "Of all the tested markers, CD24, SSEA-4, SSEA-1 (CD15) CXCR4, E-cadherin and CD44v6 were expressed on the EpCAM positive population of the tumorigenic luminal-like xenograft cells, and thus candidates for defining functionally different luminal tumor cell subpopulations." (PMID 25419568, 2014). "After 7 days, we observed more EpCAM+ tumor cells outgrowing of the explant in the treated group." (PMID 24424657, 2014).
tumor (continued). "During the progression of epithelial to mesenchymal transition both markers are downregulated and EpCAM may be downregulated to allow epithelial cell dissociation from the tumor and cytokeratin downregulated to facilitate cell plasticity and migration." (PMID 25101294, 2014). "It is suggested that this tumor may have originated from transformed C-KIT+/EpCAM+/E-cadherin+ cells, which are more primitive and undifferentiated than bipotential hepatic progenitor cells." (PMID 25202388, 2014). "In contrast to these scarce CTCs, EpCAM+ EVs might be larger in numbers, a possible multiplier in fact of EpCAM+ tumor cells in vivo." (PMID 25225495, 2014). "However, even with the use of technologies such as the FDA-approved CellSearch system, the detection of tumor cells in the blood or marrow of patients has often been limited to bulk analysis of EpCAM-positive tumor cells." (PMID 25133137, 2014). "Similar effects could be observed for different types of cell surface proteins, like EpCAM whose role of tumor progression is of comparable complexity." (PMID 25409014, 2014). "The miRNAs regulated by EpCAM control oncogenic, tumor suppressive and also metabolic functions." (PMID 25502397, 2014). "Since EMT involves at least temporary downregulation of EpCAM expression, it might influence the efficacy of EpCAM-directed therapy on tumor cells undergoing EMT." (PMID 24895575, 2014). "EpCAM also associates with the tight junction protein, claudin 7, to promote tumor cell migration rather than cell-cell adhesion that leads to lymphatic spread." (PMID 24885350, 2014). "The assumption is that since epithelial cells are not a normal component of healthy blood, any cells expressing epithelial markers must be tumor derived; however, elevated numbers of EpCAM+/CK+/CD45− cells have been found in the blood of healthy donors and patients with benign disease." (PMID 24489774, 2014). "This biomimetic approach also makes it possible to develop sensor devices for the detection of carcinoma antigens, copper ions by biomimetically synthesized quantum dots, and circulating tumor cells (CTCs) by biomimetic surfaces functionalized with epithelial-cell adhesion molecule (EpCAM)." (PMID 25490598, 2014). "Indeed, EpCAM expression among CD45– cell populations was heterogeneous in all but one (BT8) of the 12 tumor cell suspensions." (PMID 25291178, 2014). "Some studies have suggested the tumor microenvironment may be an important factor in dictating whether EpCAM will promote or inhibit tumor progression, particularly given its ability to mediate homophilic adhesive interactions between cells." (PMID 25265904, 2014). "Two studies demonstrate that this drug seems to improve progression-free survival in patients with GC (median 71 versus 44 days; P = 0.03) and that it seems to improve the survival in gastrointestinal EpCAM+ tumours (EpCAM: antiepithelial cell adhesion molecule) in intraperitoneal use." (PMID 24693422, 2014). "Interestingly, we observed differential EpCAM expression patterns with respect to the centre and invasion front of the tumor, which was identified as an independent prognostic factor." (PMID 23830302, 2013). "Recently, EpCAM has become of interest because it is a signal transducer, and a potential marker of cancer-initiating cells whose role in the development of cancer and in tumor progression depends on the tumor type." (PMID 24362576, 2013). "For overall survival, larger tumor size (≥4 cm) (HR = 3.448, P = 0.008), vascular invasion (HR = 7.135, P = 0.009), and the histologic groups of cHC-CC and EpCAM(+)/K19(+) HCC (P = 0.034) were shown to be independent prognostic factors on multivariable analysis." (PMID 24086533, 2013). "EPCAM protein was detected in 45.7% of human non-tumor mucosa samples." (PMID 24422715, 2013). "Overall, we demonstrate that CD133+/EpCAM+ tumor spheroid cells meet the key criteria of CSCs and may serve as a CSC model for both the in vitro and in vivo testing of experimental drugs." (PMID 23826249, 2013).
tumor (continued). "The expression of the selected subset of immunotherapy target genes was further evaluated by real-time PCR in sorted stromal (EPCAM−) and carcinoma (EPCAM+) cell populations from the P2726.Ov PHT and in EPCAM+ human cells from the first and ninth generation CXs of this tumor." (PMID 24278200, 2013). "Similarly to the primary specimen of origin, PiCa cells established carcinomas characterised by a focal growth and a strong expression of EpCAM at the edges of tumour areas." (PMID 23383219, 2013). "In addition, cells were analyzed by FACS for cell surface proteins which differentiate luminal versus basal/myoepithelial cells (EPCAM/CD49f) and cancer cells with tumor initiating capabilities (CD44/CD24)." (PMID 23879992, 2013). "Interestingly, both flow cytometric analysis and immunohistochemical analysis of xenograft tumors revealed that metformin significantly reduced the number of tumor-initiating EpCAM+ cells, whereas sorafenib treatment had minimal effects on TICs." (PMID 23922888, 2013). "The median cumulative survival time of patients with an increased EpCAM expression in the invasion front was the lowest with 11 months compared with 29 months of patients with a homogeneous EpCAM expression and 23 months in patients with EpCAM expression stronger within the tumor center." (PMID 23830302, 2013). "Thus, selection of patients who would benefit from EpCAM immunotherapy by determining EpCAM status in the tumor biopsies is currently undergoing vigorous evaluation." (PMID 23460885, 2013). "The aim of this work was to assess the impact on measurements of methylation of a panel of four cancer gene promoters of purifying tumor cells from colorectal tissue samples using the epithelial cell adhesion molecule (EpCAM)-immunomagnetic cell enrichment approach." (PMID 24362576, 2013). "During the progression of epithelial to mesenchymal transition both markers are downregulated; EpCAM may be downregulated to allow epithelial cell dissociation from the tumor and cytokeratin downregulated to facilitate cell plasticity and migration." (PMID 23653529, 2013). "Based on our findings, one might speculate about a differential intratumoral status of activation of EpCAM with a different expression pattern in invasion front and tumor center." (PMID 23830302, 2013). "These proliferating cells went on to form tumor spheroids enriched with CD133+/EpCAM+ cells." (PMID 23826249, 2013). "Patients were screened for: germline allele-specific expression (ASE), nucleotide variants, rearrangements and promoter methylation of mismatch repair (MMR) genes; germline EPCAM rearrangements; tumor microsatellite instability (MSI) and immunohistochemical (IHC) MMR protein expression." (PMID 24278394, 2013). "However, further investigations are necessary to study effects of EpCAM expression on cancer cells in context of tumor immunology and microenvironment." (PMID 23758908, 2013). "However, the cultured tumor spheroid cells consisted of 33.2% of CD133+/EpCAM+ cells, which is approximately 5-fold higher than the portion in the original patient tumor tissue." (PMID 23826249, 2013). "In contrast, ∼2% CD133+/EpCAM+ cells were observed in the differentiated cell xenograft tumor." (PMID 23826249, 2013). "Interestingly, we found in 42% of our study patients differential EpCAM expression patterns when comparing the tumor centre with the invasion front." (PMID 23830302, 2013). "Moreover, primary tumors with EpCAM-positive lymph node metastases displayed an advanced depth of tumor invasion (pT3/4) (p=0.046)." (PMID 23830302, 2013). "However, the difference of EpCAM expression between tumor and normal tissues dropped significantly from 4.68 to around 2, which better depicted the biological differences of EpCAM between tumor and normal cells." (PMID 24289299, 2013).
tumor (continued). "To investigate this question, we report on the correlation of circulating tumor cells using a non-EpCAM based CTC assay with standardized, semi quantitative, tumor FDG uptake metrics in patients undergoing evaluation for treatment-naïve non-small cell lung cancer (NSCLC)." (PMID 23861795, 2013). "Here we set out to test whether EpCAM-targeted MBs are capable of sensitive and specific isolation of rare tumor cells from mouse and human blood." (PMID 23516425, 2013). "In contrast, a heterogeneous EpCAM expression pattern between the centre and invasion front of the tumor was associated with a significant negative impact on survival (log rank, p=0.04)." (PMID 23830302, 2013). "Because EpCAM might be down regulated in tumor cells that underwent epithelial-mesenchymal transition, we have used an EpCAM-free detection method in order to capture as many CTCs as possible." (PMID 24058649, 2013). "In addition, EpCAM antibody conjugated AuNP-PEI-siRNA molecules would specifically target EpCAM-expressing cells RB tumor cells and spare the normal cells with low EpCAM levels." (PMID 23687439, 2013). "Double staining revealed that EpCAM and PCNA were co-expressed in numerous tumor cells, suggesting that EpCAM-positive tumor cells may have the potential to proliferate." (PMID 23251255, 2013). "Therefore, the present study was undertaken to improve the delivery of siRNA via non-toxic vehicles as well as to deliver siRNA specifically to EpCAM-expressing tumor cells." (PMID 23687439, 2013). "In tumor development and progression EpCAM has a controversial biological role." (PMID 23758908, 2013). "Therefore, the present study was undertaken to deliver siRNA specifically to EpCAM-expressing tumor cells by conjugating the EpCAM antibody to PEI-capped AuNPs." (PMID 23687439, 2013). "However, several studies have shown that the presence of EpCAM on tumor cells varies with tumor type." (PMID 23840710, 2013). "EpCAM-positive cells are captured on the microspots when whole blood is passed through the microfluidic device, and these cells are detected by analysis of the expression of tumor markers." (PMID 22396762, 2012). "In this study CD44, CD24, ABCG2, and EpCAM could be detected by flow cytometry in all the RB patient tumor samples." (PMID 22328825, 2012). "A study with a mouse xenograft model showed that fluorescent intravital live microscopy with a probe against EpCAM antigen could successfully be used for monitoring tumour resection in vivo." (PMID 22590529, 2012). "In addition, EpCAM expression was analyzed in vivo in xenograft models for tumours derived from these cells." (PMID 22590529, 2012). "We hypothesised that patients whose tumours expresed EpCAM and CK would be more likely to have CellSearch detectable CTCs." (PMID 22187035, 2012). "Indeed, in epithelial/acinar tumor cell lines with high cytokeratin expression, such as the FaDu hypopharynx carcinoma cells, EpCAM overexpression supports proliferation and cell cycle by modifying Wnt signaling." (PMID 23110550, 2012). "The coexpression of molecules such as BMP7, VCAN and EpCAM in EOC cells expressing high CD157 further substantiates this view since these molecules are considered negative prognostic markers involved in the control of the progression of various types of tumor." (PMID 22916288, 2012). "Furthermore, we provide evidence that in vitro migration of tumor cells with mesenchymal phenotype is weakly inhibited by overexpression of EpCAM." (PMID 23110550, 2012). "Furthermore, EpCAM abundance was analyzed by immunostaining of paraffin sections from tumours that were derived from the same cell lines." (PMID 22590529, 2012). "This might be due to the heterogeneous population of cells in the tumor and cell lines expressing EpCAM." (PMID 23213278, 2012).